OOSP2 (oocyte secreted protein 2)
Description:
Involved in oocyte maturation.
Synonyms: PLAC1L; TMEM122; FLJ36198; OOSP2A
Tractability: Antibody: UniProt places it where antibodies can reach, with high confidence; UniProt predicts a signal peptide or a membrane-spanning region; its Gene Ontology location is reachable by antibodies, with medium confidence.
Gene: Protein-coding gene on chromosome 11 (60,040,409 to 60,048,044, forward strand). Ensembl gene ENSG00000149507.
Subcellular location: Secreted; Cytoplasm
Gene Ontology:
Molecular function: protein binding
Biological process: oocyte maturation
Cellular component: cytoplasm; extracellular region
Homologues: Orthologues: chimpanzee OOSP2 (99% identical), pig OOSP2 (54% identical), mouse Oosp2 (53% identical). Paralogues in human: PLAC1 (28% identical), OOSP1 (25% identical).
Diseases named in the same sentence as OOSP2 in open-access papers:
OOSP2 is named in the same sentence as 1 disease in open-access papers, as found by Europe PMC text mining. Sharing a sentence is not in itself a finding about the gene and the disease. The quoted sentences say what the papers report.
viral infections (1 paper, 2025). "For example, the expression of OOSP2 was detected in a population of antigen-presenting cells in the lung that elicit a strong type 2 T helper cell (TH2)-dominated immune response to viral infections." (PMID 40440345, 2025).